TKT (transketolase)
Diseases named in the same sentence as TKT in open-access papers (continued):
Sharing a sentence is not in itself a finding about the gene and the disease.
cancer (continued). "In rapidly dividing cells such as cancer cells and stem cells, the pentose phosphate pathway activity is enhanced and transketolase expression is upregulated to meet the nucleotide demand." (PMID 40370794, 2025). "TKT expression in cancer cell cytoplasm and nuclei was significantly increased in all four relapse tissues compared to tissues at diagnosis." (PMID 40565351, 2025). "Transketolase was abnormally increased in CRC which promoted cancer cell glycolysis by enhancing AKT phosphorylation and eventually worsening CRC metastasis." (PMID 39641861, 2025). "As cancer cells have a higher rate of transketolase expression, inhibitory thiamine derivatives should preferably affect transketolases in cancer cells and contribute to a broad therapeutic index." (PMID 39444815, 2024). "As such, TKT expression can be regarded as a valuable marker for assessing the response of cancer treated with RT in the context of HCC." (PMID 38216672, 2024). "We discovered that the expression of TKT protein was obviously higher in HCC than in para-carcinoma tissues, and its expression was significantly correlated with tumor size and Edmondson grade." (PMID 38434975, 2024). "Several enzymes in the PPP non-oxidative arm, including Ribose 5-Phosphate Isomerase A (RPIA) and Transketolase (TKT) have been found to be involved in cancer." (PMID 38132097, 2023). "Next, we analyzed the paired cancer and para-cancerous tissues of 409 patients, and the data suggested that TKT expression was significantly increased in cancerous tissue." (PMID 35110545, 2022). "Because our data suggested that high TKT expression was an essential factor for cancer metastasis, we studied the role of TKT in CRC angiogenesis." (PMID 35110545, 2022). "Among Energy Metabolism ontology motifs we identified: TKT, which activity is increased in cells with heightened energy needs, such as cancer cells, while knockdown of TKT suppresses NAPDH production, increases ROS production, and inhibits the cell cycle." (PMID 33673561, 2021). "For example, oxidative PPP is often turned on due to NRF2-regulated Transketolase (TKT) overexpression to counteract oxidative stress in cancer cells." (PMID 33990217, 2021). "TKT is frequently upregulated in cancers, including cervical cancer, which was recently identified as a miR-497 target." (PMID 33803151, 2021). "In HeLa and SiHa cisplatin-resistant cells, the miR-497 downregulation ensures high levels of TKT which ultimately provides cancer cells with GSH to counteract the cisplatin-induced ROS-derived cytotoxicity." (PMID 33803151, 2021). "Despite the accumulation of R5P, knockdown of TKT suppresses tumor growth and sensitizes cancer cells to chemotherapy." (PMID 32582032, 2020). "Recent work suggests that TKT promotes genome instability by regulating nucleotide biosynthesis during liver injury and cancer initiation." (PMID 32582032, 2020). "In almost all types of cancer, both cancer cells and stromal cells like CAFs overexpress transketolase, an enzyme in the pentose phosphate pathway, which importantly produces NADPH and ribose." (PMID 30828330, 2019). "Transketolase is a pentose phosphate pathway enzyme essential for cancer growth due to its ability to control NADPH production and counteract oxidative stress." (PMID 31105878, 2019). "Transketolase is now considered one of the most universally overexpressed genes in cancer metabolism." (PMID 30828330, 2019). "TKT has recently emerged as a potential therapeutic target in cancer cells where its role in protecting against oxidative stress has been proposed to be critical." (PMID 29554142, 2018). "Combination of oxythiamine (transketolase inhibitor) with dehydroepiandrosterone (glucose-6-phosphate dehydrogenase inhibitor) was effective in arresting metatrexate-resistant cancer cell proliferation (human colon adrenocarcinoma M6-HT29)." (PMID 29208764, 2018).
cancer (continued). "The transketolase is required for cancer growth because of its ability to affect the production of NAPDH to counteract oxidative stress." (PMID 28496442, 2017). "Metabolizing glucose through the PPP and transketolase to generate NADPH is a metabolic strategy observed in cancer cells, activated macrophages and the growth of T cells in response to pathogen challenge." (PMID 25188286, 2014). "Silencing TKT in the cancer cells obviously abolish the cross-talk between PPP and glycolysis, causing deficiency in utilizing glycolytic metabolites for down-stream biosynthesis and energy production in the cells." (PMID 24666435, 2014). "The PPP and in particular the thiamine-dependent enzyme TKT is essential for cancer cells to synthesize large amounts of nucleic acids needed for rapid cellular growth." (PMID 24280319, 2013). "TKT inhibitors are being considered fordevelopment for cancer therapy because TKT activity is upregulated in proliferativecells, and specificity for TKT enzymes in cancer cells can therefore be achievedthrough targeting an upregulated metabolic process." (PMID 22645655, 2012). "In particular, the two key enzymes G6PDH and TKT have been shown to play a critical role in cancer cell cycle progression in the HT-29 cell line." (PMID 21849056, 2011). "This approach resulted in the identification of two novel small-molecule inhibitors, which inhibit human TKT and suppress proliferation of cancer cell lines." (PMID 16465194, 2006). "TKT inhibitors, such as oxygen thiamine (OT) and Oroxylin A, are gaining increasing attention for their ability to disrupt key metabolic processes that support cancer cell proliferation and therapeutic resistance." (PMID 40230848, 2025). "In the future, combining TKT inhibitors like OT and Oroxylin A with traditional chemotherapy holds significant potential as a strategy to overcome resistance and enhance treatment outcomes across a wide range of cancers." (PMID 40230848, 2025). "We therefore hypothesized that elevated TKT expression in cancer facilitates tumor growth and metastasis by altering glucose metabolism." (PMID 40230848, 2025). "Overall, these findings suggest that TKT may play a role in cancer cell metabolism and immune interactions, making it a promising target for further investigation in precision oncology strategies." (PMID 40230848, 2025). "Additionally, increased activation of NRF2 in cancer cells results in elevated expression of enzymes involved in intermediate metabolism, such as transketolase (TKT) and G6PD." (PMID 38247494, 2024). "PFKFB4 up-regulates TKT expression by driving SRC-3 activation and glucose flow to the PPP, thereby providing conditions for rapid division and proliferation, and causing proliferation and metastasis of cancer cells." (PMID 38434975, 2024). "Therefore, targeting TKT metabolic pathways introduce a new clue for the development of future cancer therapies." (PMID 35752610, 2022). "Moreover, TKT overexpression has been correlated with tumor invasiveness and poor cancer prognosis in lung, prostate, and breast cancer cells." (PMID 36497226, 2022). "TKT inhibition may thus be a useful strategy to intervene in cancer cell invasion and metastases, and need to be explored a large cohort of clinical trial." (PMID 35711845, 2022). "Taken together, our results uncover an unexpected role of oroxylin A in TKT inhibition for the first time, which may offer new opportunities for the discovery of new scaffolds and new application of TKT inhibitors as well as cancer therapy." (PMID 36314067, 2022). "Among six drug targets under consideration, deactivation of transketolase and glucose-6-phosphate isomerase may be the most potential to slow down cancer progression by reducing cell proliferation, growth, fermentation and energy supply." (PMID 33510857, 2021).
cancer (continued). "However, as happens in the cancer-case study, some activities can be interdependent, such as the two activities (R13 and R14) catalyzed by transketolase (TKT), or can be assumed to behave as a coordinated block." (PMID 34297714, 2021). "Therefore, targeting the metabolic enzyme TKT is an attractive strategy for bile acid metabolism in livers and cancer therapy." (PMID 31949131, 2020). "Reversal or prevention of transketolase oxidation at residue Cys157 by drug delivery or gene therapy may offer an effective way to prevent antioxidant production and hence proliferation in cancer cells." (PMID 32139871, 2020). "TKT pathways are also intricately involved in cancer progression and metastasis." (PMID 30646877, 2019). "Furthermore, TKTL1 has been extensively investigated in cancers, and it has been supposed to be a catalytically active mutant form of human TKT, through formation of heterodimers with other TKT isoforms and/or by activation of other thiamine derivatives." (PMID 28143530, 2017). "Thus, TKTL1 drives the glucose metabolism and contributes to the Warburg effect in cancer cells through its transketolase activity." (PMID 27391434, 2016). "Inhibition of the activity of the key enzymes (e.g., transketolase/transadolase) in these metabolic networks, resulting in significant limitation of glucose utilization, provides an ideal strategy for an effective therapy of cancer." (PMID 23890079, 2013). "However, the lack of activity of purified TKTΔ38 in solution contradicts reports describing the TKT activity of TKTL1 when exogenously overexpressed or repressed in cancer cells." (PMID 24280319, 2013). "However, the pathway is also significant in cancer cell metabolism, through the Warburg effect and the overexpression of a mutant form of the human transketolase (TKTL1) in various cancer cell lines." (PMID 23776642, 2013). "TKTL1, an altered isoform of the transketolase gene, is upregulated in many human cancers." (PMID 21854597, 2011). "Our findings strongly indicate that overexpression of TKTL1 is responsible for the observed tumour-specific effects of transketolase enzyme reactions, and represents the basis for the observed inhibition of proliferation of cancer cells by anti-transketolase approaches." (PMID 16465194, 2006). "Furthermore, several natural products have been reported to inhibit transketolase enzyme activity in vitro, and also to inhibit cell proliferation or suppress tumour growth in mouse models or cancer patients as a result of reduction of transketolase activity." (PMID 16465194, 2006). "The determination of TKTL1 expression in human malignancies may help to identify cancer patients that would benefit from an anti-transketolase cancer therapy." (PMID 16465194, 2006). "The only transketolase gene overexpressed in carcinoma tissue was the TKTL1 gene." (PMID 16465194, 2006). "As a result, transketolase could be an effective target for cancer treatment." (PMID 40956032, 2025). "Further, high enrichment scores for stemness gene sets in the high TKT group suggest that TKT may be involved in maintaining cancer stem cell properties such as unlimited proliferation and self-renewal, contributing to tumor heterogeneity, recurrence, and resistance to therapies." (PMID 40230848, 2025). "These correlations imply that TKT may be involved in various metabolic processes critical for tumor progression, such as nucleotide biosynthesis and redox balance, which are essential for cancer cell survival and proliferation." (PMID 40230848, 2025). "Additionally, we found a positive association between TKT and macrophages in most cancers and a negative correlation with some effector immune cells, such as resting CD4+ memory T cells and activated natural killer (NK) cells." (PMID 40230848, 2025).
cancer (continued). "Several enzymes in the oxidative (e.g., G6PD) as well as non-oxidative (e.g., TALDO1, TKT) phases of pentose phosphate pathway was highly expressed in pRCC type 1, associated with increased demand for ribonucleotides in the rapidly proliferating cancer cells." (PMID 38703764, 2024). "Thus, TKT is a potential therapeutic target for cancer therapy." (PMID 36314067, 2022). "In this context, deactivation of transketolase and glucose-6-phosphate isomerase may be considered as potential drug targets to resist cell growth, fermentation and proliferation as well as energy supply in human cancer cells." (PMID 33510857, 2021). "Finally, the discovery of a redox-sensitive regulatory system that activates transketolase, potentially during oxidative stress, could have important implications for future advances in cancer treatments." (PMID 32139871, 2020). "Moreover, to confirm the metabolic effects of pioglitazone we investigated key proteins indicative of altered glucose metabolism in cancer cells, such as the transporters Glut-1 and SLC15A (Solute-linked carrier family A1 member 5), G6PD (glucose-6-phosphate dehydrogenase) and TKTL1 (Transketolase)." (PMID 31027492, 2019). "Moreover, our characterization of transketolase as a metabolic checkpoint mediator might inform other areas of biology where this enzyme and its downstream targets are important, such as during cancer cell proliferation." (PMID 25188286, 2014). "Consequently, small-molecule inhibitors of transketolase, such as those developed as anti-cancer therapies, could hold promise for combating recalcitrant intracellular fungal pathogens." (PMID 25188286, 2014). "The activity of these compounds, confirmed in transketolase cell extract and in two cancer cell lines, suggests that the phenyl urea scaffold could be used as novel starting point to generate new promising chemotherapeutic agents by targeting human transketolase." (PMID 22403640, 2012). "Transketolase and TKTL1 regulate various cancer‐related events, including cancer cell proliferation, metastasis, invasion, epithelial‐mesenchymal transition, chemoradiotherapy resistance, and patient survival and prognosis." (PMID 40956032, 2025). "For example, blocking TKT was proved to prevent the development of HCC, which demonstrated the important role of PPP in cancer development." (PMID 39991762, 2025). "Transketolase (TKT) is a key enzyme linking glycolysis and PPP, whose inhibition improves the efficiency of cancer treatment." (PMID 39991762, 2025). "Being an enzyme that is important for cell biosynthesis, TKT, as well as both the TKTL1 and TKTL2 isoenzymes, have turned out to be important prognostic markers and potential regulatory targets in various cancer types." (PMID 41302487, 2025). "TKT, a critical enzyme linking the PPP and glycolysis, plays a central role in this metabolic shift, suggesting its potential influence on cancer cell metabolism." (PMID 40230848, 2025). "Consistent with the hyper-proliferative nature of cancer cells, increased protein levels of glucose 6-phosphate dehydrogenase (G6PD) and transketolase (TKT) were documented in HBV- and HCV-related HCC patients." (PMID 37108625, 2023). "Cytokeratin 5 (CK5) and transketolase (TKT) were identified in benign mixed tumor cells and complex carcinoma cells." (PMID 37893211, 2023). "TKT, a key enzyme of the non‐oxidative PPP, plays a crucial role in carbohydrate transformation by supplying cancer cells with R5P for ribonucleotide synthesis." (PMID 36314067, 2022). "The expression of TKT (P < 0.001) and TKTL2 (P < 0.05) mRNA were dramatically higher in cancer than the normal tissues." (PMID 35711845, 2022). "Elevated levels of NRF2 in cancer induce the upregulation of glucose 6-phosphate dehydrogenase (G6PD), transketolase (TKT), 6-phosphogluconate dehydrogenase (PGD), and other metabolic enzymes." (PMID 33808001, 2021).
cancer (continued). "The G6PD, PGD, TKT, and TALDO1 support glucose flux and generate purines, which are building blocks of DNA and RNA, which help to accelerate proliferation in cancer cells." (PMID 33922165, 2021). "When the PI3K/Akt signaling pathway is activated, NRF2 directly increases G6PD, 6PGD, TKT, and TALDO expression to enhance metabolic activities and promote cancer cell growth." (PMID 32582032, 2020). "Here, we investigate the expression of TKT and TKTL1 in canine mammary tissues by immunohistochemistry, exploring hyperplastic lesions as well as benign and malignant tumors, including simple and complex types." (PMID 28143530, 2017). "In cancer cells, the PPP catalyzed by TKT plays an important role in utilizing glucose for ribose-5-phosphate synthesis." (PMID 24666435, 2014). "Western blot analysis indicated that TKT expression was slightly over-expressed in the UM1 and UM2 cancer cells when compared to NHOKs." (PMID 24666435, 2014). "SiTKT transfection led to a significant decline in the expression of TKT in both UM1 and UM2 cancer cells." (PMID 24666435, 2014). "Among them, galectin-3-binding protein and ALDH1A1 were found preferentially elevated in TNBC, whereas CK19, transferrin, transketolase, and thymosin β4 and β10 were elevated in HER2-positive cancers." (PMID 22110952, 2011). "This complex interplay of epigenetic and transcriptional regulation highlights the central role of TKT in cancer metabolism, suggesting its potential as a therapeutic target, particularly in terms of inhibiting the STAT3-TKT signaling pathway and regulating TKT expression." (PMID 40230848, 2025). "Transketolase enzymes involved in the nonoxidative phase are upregulated in various cancers to aid cancer cell proliferation and metastasis." (PMID 40956032, 2025). "Activation of TKT by STAT3 may drive metabolic reprogramming by enhancing the flow of glucose in the PPP, thereby enhancing cancer cell survival and proliferation." (PMID 40230848, 2025). "MS17 induced the upregulation of PRDX2 and TKT with the TALDO1 downregulation in SW620 cells, which may interfere with the cancer metabolism and increase ROS production to induce cellular stresses, leading to apoptosis." (PMID 38542474, 2024). "TKT protein was highly expressed in 54% (108/200) HCC samples, which was situated major in the cytoplasm of cancer, the expression of TKT was also recorded in non-tumor mucosa." (PMID 38434975, 2024). "In a comparison of the control with cancer group (grade 4), the 5-marker panel (CCT3, PCMT1, TKT, TOMM34, UBA1) showed better sensitivity (0.90 and 0.90), specificity (0.93 and 1.00), error rate (8 and 4%), and AUC value (0.94 and 0.96) than the best single marker (TOMM34)." (PMID 37875819, 2023). "Furthermore, the DNP fraction was enriched with proteins relating to glycolysis and other metabolic pathways upregulated in cancer, including lactate dehydrogenase A (LDHA), transketolase, and β-hexosaminidase." (PMID 36310768, 2022). "Several studies have reported upregulation of TKT and TALDO in several types of cancer." (PMID 36497226, 2022). "The finding that S100A11 decreased the activity of the PPP, of which TKT is a key enzyme, prompted us to investigate whether S100A11 regulates the expression of TKT for the survival and biosynthesis of cancer cells." (PMID 35752610, 2022). "In addition, it has been reported that TKT counteracts oxidative stress by supplementing NADPH, which is beneficial to cancer growth." (PMID 36253417, 2022). "Daily administration of 500 mg/kg OT considerably inhibited metastases and N3’-pyridyl thiamin, as a thiamin antagonist, totally inhibited the expression of transketolase in HTC-116 cell lines without any effect on the cancer cell growth." (PMID 35603057, 2022).